CXCL10 (C-X-C motif chemokine ligand 10)
Diseases named in the same sentence as CXCL10 in open-access papers (continued):
Sharing a sentence is not in itself a finding about the gene and the disease.
endometrial cancer (5 papers, 2014 to 2025). Primary or metastatic malignant neoplasm involving the endometrium (mucous membrane that lines the endometrial cavity). "TPX2 affects the malignant progression of endometrial cancer cells by coupling the CX3CR1/CXCL10 chemokine pathway to the PI3K/Akt signaling pathway." (PMID 40511304, 2025). "In advanced endometrial cancer, CXCL10 was shown to antagonize fibroblast growth factor action, thereby inhibiting angiogenesis." (PMID 38957317, 2024). "Sp1 regulates TPX2 expression, resulting in a cascade effect, in EC; it affects the malignant progression of endometrial cancer cells by coupling the CX3CR1/CXCL10 chemokine pathway to the PI3K/Akt signaling pathway." (PMID 38466034, 2024). "Sp1 negatively regulated TPX2 expression, affecting the malignant progression of endometrial cancer cells by coupling the CX3CR1/CXCL10 chemokine pathway to the PI3K/Akt signaling pathway." (PMID 38466034, 2024). "Therefore, five endometrial cancer cell lines were treated with DMSO, 100nM, 200nM, and 500nM of AZD1775, and qRT-PCR was employed to measure the expression of CCL5, CXCL10, and IFNB1." (PMID 38169513, 2024).
eosinophilia (5 papers, 2009 to 2024). "CXCL10 upregulation in eosinophilic asthmatic mice has been linked to increased airway hyperreactivity, eosinophilia, and CD8+ T cell recruitment, all of which were evident in TLR7 KO mice at 14 dpi." (PMID 39769461, 2024).
exanthema (5 papers, 2015 to 2026). "Analysis of the association between increased cytokine levels and ZIKV symptoms indicated that CXCL10 (p = 0.0029) was associated with exanthema, while IL-5 (p = 0.0496) was linked to headache." (PMID 37235332, 2023). "Additionally, the development of rash and higher serum CXCL10 levels were positively correlated with improved survival." (PMID 41598579, 2026). "Interestingly, exanthema was strongly associated with IFN-γ (p = 0.0017), IL-4 (p = 0.0018), IL-5 (p = 0.0047), and CXCL10 (p = 0.0029)." (PMID 37235332, 2023). "These analyses showed that serum CXCL9 and CXCL10 levels were elevated in AOSD patients with an evanescent rash compared with patients who did not display such a manifestation." (PMID 28436448, 2017). "CXCL10 levels rose mainly during the final phase of the disease (T2), whereas IFN-γ has a major increment during the PR “intermediate” phase, corresponding to the peak of the clinical manifestation of the exanthem." (PMID 26451078, 2015). "An analysis of serum chemokine levels with regard to AOSD manifestations showed that patients with a skin rash had a higher level of CXCL9 (667.6 ± 823.2 vs. 105.8 ± 84.8 pg/mL, p = 0.024) and CXCL10 (251.6 ± 191.2 vs. 79.4 ± 45.6 pg/mL, p = 0.021) than those without a rash." (PMID 28436448, 2017).
Flavivirus Infections (5 papers, 2019 to 2025). Infections with viruses of the genus FLAVIVIRUS, family FLAVIVIRIDAE. "CXCL10 and CXCL11 are chemokine markers of the IFN-I response, and they are induced by IFN during flavivirus infections." (PMID 40431659, 2025). "Consistent with flavivirus infection in IFNAR−/− mice and humans, YF challenge in A129 mice induced the hyper-production of IP-10 (CXCL10) which plays a significant role in disease outcome and survival." (PMID 36871059, 2023). "In order to investigate the response of the respiratory epithelium upon flavivirus infection, we measured the expression levels of type I and type III IFNs and the pro-inflammatory cytokines IL-6, IL-8/CXCL8, and IP-10/CXCL10." (PMID 31057517, 2019). "Additionally, excluding for JEV, flavivirus infection did not induce a significant IFN response in comparison to mock controls and led to the activation of NECs, indicated by an increase in the expression of the inflammatory mediators IL-8/CXCL8 and IP-10/CXCL10." (PMID 31057517, 2019).
fungal infections (5 papers, 2019 to 2025). "The results of studies indicate that IL15, FLT3L, CXCL10, and IL1B, which demonstrated the most promising outcomes among the estimates, are actually associated with numerous viral, bacterial, parasitic, and fungal infections." (PMID 40650062, 2025). "Furthermore, alloSCT patients with no fungal infection showed lower CXCL10 concentrations in comparison to patients with proven or probable IA, being highest in those patients who survived IA42." (PMID 31754120, 2019).
Graves ophthalmopathy (5 papers, 2014 to 2022). An autoimmune disorder of the EYE, occurring in patients with Graves disease. "Also, evidence indicated that CCL2 and CXCL10 chemokines, modulated by cytokines and PPARγ agonist, play an important role in Graves’ ophthalmopathy." (PMID 35242125, 2021). "Also, evidence indicates CCL2 and CXCL10 chemokine modulations by cytokines and PPARγ agonist in Graves’ ophthalmopathy." (PMID 34054797, 2021).
Headache (5 papers, 2018 to 2025). Cephalgia, or pain sensed in various parts of the head, not confined to the area of distribution of any nerve. "Headache was associated with significant increase in CXCL10, CXCL11, MCSF, MCP-2 and TNF-alpha, while fatigue was associated with significant increases in CXCL10, MCP-4 and TNF-α." (PMID 38235127, 2023). "Serum CXCL10 levels correlated with dizziness and headache severity in VM patients." (PMID 41249857, 2025).
juvenile idiopathic arthritis (5 papers, 2005 to 2025). Juvenile idiopathic arthritis (JIA) is the term used to describe a group of inflammatory articular disorders of unknown cause that begin before the age of 16 and last over 6 weeks. "Synovial CXCL10 expression is highly elevated in juvenile idiopathic arthritis (JIA) and, interestingly, raised levels of CXCL4 in plasma have also been observed in a subset of RA patients, specifically in those with vascular lesions." (PMID 36275816, 2022).
liver cirrhosis (5 papers, 2016 to 2025). "By univariate logistic regression analysis, rs12979860 CC genotype, CXCL10, CXCL11, CCL3, CCL4 and liver cirrhosis were the factors for non-NR." (PMID 29284412, 2017). "CXCL10, CXCL11, CCL3, CCL4 and liver cirrhosis were the predictive factors for non-NR by univariate logistic analysis, but only the CCL4 was the independent predictor for non-NR by multivariate logistic analysis." (PMID 29284412, 2017).
liver dysfunction (5 papers, 2021 to 2025). "Among these chemokines, CXCL9 and CXCL10 showed the strongest association with advanced severity of liver dysfunction as defined by CTP, MELD-Na, and MELD 3.0 scores and were predictive of 30-day mortality." (PMID 41373861, 2025). "The role of CXCL10/IP10 has been demonstrated in DENV severity associated with the induction of vascular leakage and a novel association with changes in liver dysfunction." (PMID 34959637, 2021). "In particular, CXCL9 and CXCL10 may have potential for discrimination of severe liver dysfunction and poor short-term prognosis." (PMID 41373861, 2025). "Moreover, in Brazil, the increases in IL-10, macrophage migration inhibitory (MIF), and C–X–C-motif chemokine 10/interferon gamma-induced protein 10 (CXCL10/IP-10) during the acute phase in severe cases have been reported to be correlated with hepatomegaly and liver dysfunctions." (PMID 39200005, 2024). "However, we observed a significant correlation between preoperative CXCL10 levels and laboratory parameters of liver dysfunction (AST: Rs = 0.304, p = 0.001; bilirubin: Rs = 0.370, p = 0.001; ALP: Rs = 0.286, p = 0.002) as well as between baseline CXCL13 levels and CRP (Rs = 0.344, p = 0.001)." (PMID 36077611, 2022).
macrophage activation syndrome (5 papers, 2020 to 2022). A complication of rheumatic disease that is caused by excessive activation and uncontrolled proliferation of T lymphocytes and well-differentiated macrophages. "Increased levels of IFNγ-induced chemokines such as CXCL9, CXCL10, and CXCL11 were found to be associated with sJIA complicating macrophage activation syndrome." (PMID 35268506, 2022). "In particular, the levels of CXCR9, CXCL10, CXCL11, and IL–18 were elevated in SJIA patients with macrophage activation syndrome compared with active SJIA without macrophage activation syndrome." (PMID 34884842, 2021).
mastitis (5 papers, 2017 to 2025). Inflammation of breast tissue during lactation or postpartum due to an obstructed duct or infection. "Notably, the study underscores the roles of chemokines CCL8, CCL2, and CXCL10 in immune cell recruitment during mastitis, where their downregulation suggests impaired mammary immune defense that governs Chemokine signalling pathways." (PMID 40196120, 2025).
meningoencephalitis (5 papers, 2019 to 2025). Inflammation of the meninges and brain, generally secondary to an infectious cause. "In the same study, serial CSF analysis revealed that one meningoencephalitis case exhibited progressive increases in neopterin and CXCL-10 levels until the patient’s death, while a rhombencephalitis case showed a decrease in biomarker levels until the patient was discharged from the hospital." (PMID 39861878, 2025).
nasal polyps (5 papers, 2015 to 2025). "has suggested that CXCL10 stimulation can trigger the infiltration of Th1 cells into nasal polyps." (PMID 34291079, 2021).
ocular toxoplasmosis (5 papers, 2014 to 2025). Ocular toxoplasmosis is an infection in the eye caused by the parasite, Toxoplasm a gondii. "Cxcr3 signaling is required for recruitment of cytotoxic T cells in West Nile virus encephalitis, and in the eye, Cxcl10 mediates Th1 T cell trafficking in response to chronic ocular Toxoplasmosis." (PMID 25595590, 2015). "CXCL10 is required to maintain T-cell populations and to control parasite replication during chronic ocular toxoplasmosis." (PMID 24661782, 2014). "An antibody targeted to CXCL10 reduces the migration of CD4- and CD8-positive T cells into the retina, and promotes intraocular parasite replication and retinal damage in mouse ocular toxoplasmosis, emphasizing the role of CXCL10 in protecting the infected eye." (PMID 40137771, 2025). "In another study, patients with ocular toxoplasmosis displayed high levels of IFN-induced chemokines CXCL9 and CXCL10 and circulating chemokines CCL25, CCL11, CXCL12, CXCL13, and CCL2." (PMID 36755348, 2023).
oral cancer (5 papers, 2017 to 2023). "GSEA of oral cancers stratified by CXCL10/STAT2 expression showed that activation of T-cell pathways and increased tumor infiltration scores of Type 1 T helper (Th1) and CD8+ T cells were associated with high CXCL10/STAT2 expression." (PMID 35207629, 2022). "Instead, they conduct a cell-based study and find that knockdown of CXCL10 in oral cancer cells leads to reduction of cell proliferation, migration and invasion, which suggests an oncogenic role of CXCL10 in this in vitro cell model." (PMID 35207629, 2022). "A recent meta-study found that increased tumor infiltration with Th1 and CD8+ T cells was associated with the expression status of STAT2 and its target CXCL10, suggesting that the activation of this pathway could predict the outcome in oral cancer patients." (PMID 38001683, 2023). "The prognostic values of the core enriched genes in interferon-α/γ pathways were examined in TCGA data set and were validated in another oral cancer cohort (GSE65858), which resulted in CXCL10 and STAT2." (PMID 35207629, 2022). "It is worth specifically examining the biomarker role of CXCL10/STAT2 in responses to anti-EGFR and ICB-based therapies in oral cancer patients." (PMID 35207629, 2022). "The prognostic values of CXCL10 and STAT2 are confirmed in another validation cohort (GSE65858) that contains 83 oral cancer cases." (PMID 35207629, 2022). "After validating in another oral cancer cohort (GSE65858), high expressions of C-X-C motif chemokine ligand 10 (CXCL10) and Signal transducer and activator of transcription 2 (STAT2) were confirmed to be good prognostic biomarkers." (PMID 35207629, 2022). "For example, CXCL10 can attract the cytotoxic CD8+ T cells to the TME for cancer killing, and the high expression of CXCL10 in the TME can predict a good prognosis in oral cancer patients." (PMID 35455671, 2022). "Although the clinical information is not publicly available for these 4 oral cancer data sets, it is possible that the patients with high CXCL10/STAT2 expression also have a more favorable outcome than those with low CXCL10/STAT2 expression." (PMID 35207629, 2022). "In addition, the expressions of CXCL10 and STAT2 in oral cancer were also correlated in TCGA (r = 0.677, p < 0.001) and GSE65858 (r = 0.617, p < 0.001) cohorts." (PMID 35207629, 2022). "High expressions of CXCL10 and STAT2, which are correlated with activation of T-cell pathways and tumor infiltration of Th1 and CD8+ T cells, are good prognostic biomarkers for oral cancer patients." (PMID 35207629, 2022). "Thus, the cell autonomous and non-autonomous functions of CXCL10 in the tumor microenvironment of oral cancer may need to be further investigated." (PMID 35207629, 2022).
osteoporosis (5 papers, 2021 to 2025). A condition of reduced bone mass, with decreased cortical thickness and a decrease in the number and size of the trabeculae of cancellous bone (but normal chemical composition), resulting in increased fracture incidence. "Firstly, in terms of osteoporosis risk assessment, the 7 inflammatory factors we identified (Artemin, β-NGF, CXCL10, CXCL6, IL-10Rα, IL-10Rβ, LAP-TGFβ1) may become new biomarkers." (PMID 41261570, 2025). "Therefore, possible osteoclast-stimulating factors released from mast cells that could be involved in osteoporosis development might be Midkine and/or CXCL-10, which needs to be verified in future studies." (PMID 37298085, 2023). "Subcluster analysis disclosed overall highest 31.86% CXCL10-PCC parathyroid chief cells, but SPARCL1-OC parathyroid oxyphil cells were higher in osteoporosis patients." (PMID 40496565, 2025). "In both non-osteoporosis and osteoporosis patients, cell communication analysis revealed that CXCL10-PCC, HSPA1A-OC, and SPARCL-OC are predominantly involved in cell-to-cell contact." (PMID 40496565, 2025). "In patients suffering with osteoporosis, SPARCL1-OC followed by HSP1IA-OC parathyroid oxyphil cells were highly clustered, while in non-osteoporosis patients CXCL10-PCC followed by S100A13-PCC parathyroid chief cells were highly clustered." (PMID 40496565, 2025).
ovarian tumors (5 papers, 2019 to 2025). "In our system, the SASP program triggered by cisplatin therapy in Brca1-deficient ovarian tumors was limited to Ccl5, Cxcl10, and Il6 of the factors examined." (PMID 35082152, 2022). "Combined with our previous work demonstrating the presence of cleaved CXCL10 in tumour tissue, our data strongly indicate that these discrepancies relate to the relative levels of biologically active versus modified CXCL10 associated with ovarian tumours." (PMID 34200333, 2021). "In fact, higher CXCL10 levels have been correlated with greater T-cell infiltration in ovarian tumors, while its silencing results in immune exclusion and poor outcomes." (PMID 41463176, 2025). "We previously identified that whilst CXCL10 is abundant in ovarian tumour tissue, it is often present in a truncated form." (PMID 34200333, 2021). "On the other hand, the pathway can activate IRF3 and significantly increase the expression of CCL5 and CXCL10, which leads to T cell recruitment and enhances the function of lymphocytes in ovarian tumors." (PMID 34620163, 2021). "CXCL10 is secreted by cancer cells in vitro in response to inflammatory stimuli; and in “immunoreactive” ovarian tumours, with increased relative expression of CXCL10 and CXCR3, there is increased recruitment of T-lymphocytes and subsequent positive impact on survival." (PMID 34200333, 2021). "Post-translational processing of CXCL10 by DPP4 may thus explain observed discrepancies between CXCL10 abundance and poor leukocyte infiltration into ovarian tumour tissues." (PMID 34200333, 2021). "Lastly, we show that the combination of high mRNA expression levels for three IFN-γ target genes (CXCL10, CXCL11 and IFI16) correlated with overall survival in ovarian tumors from the TCGA database, pointing to the potential clinical significance of this pathway in HGSOC." (PMID 31840082, 2019). "Despite these well-established roles, CXCL10 expression in ovarian tumours fails to suppress tumour growth as anticipated; over-expression of CXCL10 can lead to enhanced lymph node metastasis, whilst decreased plasma CXCL10 concentration has been correlated with positive prognosis." (PMID 34200333, 2021).
prediabetes (5 papers, 2015 to 2021). "That is, in the islet of prediabetes animal, β cells can regulate the autoimmune response by producing CXCL10, under the action of inflammatory factors such as IFN-γ and TNF-α." (PMID 35242125, 2021). "Additionally, prediabetes animal studies suggested that CXCL10 is one of the major chemokines expressed in vivo in the islet environment." (PMID 35242125, 2021).
primary immunodeficiency (5 papers, 2018 to 2025). "Given the epigenetic control over primary immunodeficiency and TNF/MAPK signaling pathway regulation, ChIP-qPCR was used to detect histone marker enrichment in CXCL10 and MECOM genes." (PMID 40805064, 2025). "As primary immunodeficiency-related genes were correlated with TfR1 low-expressed cells, we detected fold changes of PD-L1, CXCL9, and CXCL10 mRNA levels in TfR1-knockout cells, which were enhanced after IFN-γ treatment." (PMID 32024821, 2020).
prion disease (5 papers, 2014 to 2021). A transmissible disease that is caused by a protein that is able to induce abnormal folding of normal cellular proteins, leading to characteristic spongiform brain changes, which are associated with neuronal loss without an inflammatory response. "Our CISH results suggested that during prion disease, the predominant cell type producing Cxcl10 was astrocytes." (PMID 32381108, 2020). "Firstly, we looked at levels of cytokines/chemokines known to be induced in prion disease (Cxcl10, Il-12b and Il-1b)." (PMID 24655482, 2014). "It is now accepted that prion diseases have a neuroinflammatory component that may play a critical role in neurodegeneration, with increases in numerous proinflammatory cytokines and chemokines such as IL-1α and β, IL-12p40, TNF, CCL2–CCL6, and CXCL10 in the brains of mice with clinical disease." (PMID 30650564, 2019).
retinal ischemia (5 papers, 2015 to 2025). A ischemic disease that involves the retina. "IP-10 (CXCL10), in particular, showed one of the largest fold changes between groups, reinforcing its emerging role as a biomarker of retinal ischemia and inflammation." (PMID 40650239, 2025). "In a mouse model of retinal ischemia, ER stress was essential for the induction of CXCL10 expression." (PMID 36359735, 2022). "The expression of CXCL4, which binds with low affinity to CXCR3, was elevated after retinal ischemia though expressed later than CXCL10." (PMID 26448323, 2015). "Given that CXCL10 and its receptor CXCR3 are involved in retinal inflammation and neuronal injury, it would be important to understand the potential mechanisms underlying the upregulation of this pathway after retinal ischemia." (PMID 26448323, 2015). "The mRNA and protein expression levels of CXCL10 and CXCR3 were significantly increased after IOP-induced retinal ischemia." (PMID 26448323, 2015). "CXCL10 is a key microglia-activating cytokine that is produced by damaged neurons and genetic deletion of its microglial/macrophage receptor CXCR3 resulted in reduced neuronal death after retinal ischemia." (PMID 36359735, 2022).
RSV bronchiolitis (5 papers, 2011 to 2024). "Among the most abundant chemokines in infants suffering from RSV bronchiolitis are CXCL10/IP-10, CXCL8/IL-8, CCL2/MCP-1 and CCL3/MIP-1α." (PMID 34320038, 2021). "McNamara and colleagues reported that IP-10/CXCL10 is one the most abundant cytokines in bronchoalveolar lavages (BAL) form infants with RSV bronchiolitis." (PMID 29215596, 2017).